PRNT (prion locus lncRNA, testis expressed)
Synonyms: M8
Gene: Long non-coding RNA gene on chromosome 20 (4,731,279 to 4,740,668, reverse strand). Ensembl gene ENSG00000180259.
Subcellular location: Secreted
Diseases named in the same sentence as PRNT in open-access papers:
PRNT is named in the same sentence as 11 diseases in open-access papers, as found by Europe PMC text mining. Sharing a sentence is not in itself a finding about the gene and the disease. The quoted sentences say what the papers report.
colon cancer (2 papers, 2022 to 2024). "Analysis of datasets showed PRNT upregulation in OXA-resistant colon cancer along with downregulation of HIPK2." (PMID 39062921, 2024). "By performing in vitro and in vivo studies, the authors found that PRNT upregulation induces colon cancer cell migration, resistance to OXA and tumor growth." (PMID 39062921, 2024). "Mechanistically, PRNT regulates HIPK2 mRNA expression in colon cancer by sponging ZNF184 transcription factor." (PMID 39062921, 2024). "In a recent study trying to identify long non-coding (lnc) RNA and mRNA associated with oxaliplatin resistance, the authors found that lncRNA prion protein testis specific (PRNT) is upregulated in colon cancer." (PMID 39062921, 2024).
scrapie (2 papers, 2018 to 2019). A fatal disease of the nervous system in sheep and goats, characterized by pruritus, debility, and locomotor incoordination. "Until now, the causal effect of the PRND and PRNT genes on scrapie susceptibility was unclear because this effect could be induced by an LD block." (PMID 31649311, 2019). "Because goats are another major host of scrapie, we searched for such genetic linkage in the scrapie-associated SNPs among the PRNP, PRND and PRNT genes in Korean native black goats." (PMID 30359416, 2018).
PRNT also shares sentences with these, for which no sentence is quoted: tumor (8 papers); cancer (7); infection (3); melanoma (2); viral infections (2); asthma (1); breast carcinoma (1); dengue (1); lung adenocarcinoma (1).